USP7 (ubiquitin specific peptidase 7)
Diseases named in the same sentence as USP7 in open-access papers (continued):
Sharing a sentence is not in itself a finding about the gene and the disease.
cancer (continued). "Moreover, USP7 also induced unfolded protein accumulation causing ER stress in cancer cells, which leads to oxidative stress to induce DNA damage." (PMID 34469054, 2021). "Increased levels of OGT or USP7 are associated with human cancers." (PMID 26678539, 2015). "Therefore, a drug that prevents the formation of the Hdm2/USP7 complex or inhibits its catalytic activity will benefit patients with cancer associated with a dysregulated Hdm2 protein." (PMID 25605410, 2015). "Collectively these data indicates that USP7 depletion may cause genomic instability, one of the hallmarks of cancer." (PMID 25003721, 2014). "Furthermore, USP7 depletion has been associated with reduced EZH2 levels in HCT116 cancer cells." (PMID 39310812, 2024). "USP7 is known to be occasionally overexpressed in several cancers, and this overexpression has been reported to be closely associated with the chemoresistance of tumors to anticancer chemical drugs and increased metastatic ability, resulting in poor clinical outcomes in patients with cancer." (PMID 38474017, 2024). "In addition, bioinformatics analyses of transcriptomic datasets from Cancer Cell Line Encyclopedia database revealed significantly positive associations between USP7 expression and CYR61/CCN1 (R = 0.4498, p < 0.0111), CTGF/CCN2 (R = 0.3141, p < 0.0426) in 31 HNSCC cell lines." (PMID 35931679, 2022). "Therefore, given the association between USP7 and cancers, targeting USP7 could provide a potential therapeutic strategy in cancer treatment." (PMID 34869041, 2021). "Therefore, given the association between USP7 and cancers, targeting USP7 could be considered as an attractive and potential therapeutic approach in cancer treatment." (PMID 34869041, 2021). "Ubiquitin-specific protease 7 (USP7) is a multifunctional deubiquitinase that has emerged as an important regulator of cancer progression, with growing evidence linking it to tumor immune evasion, metabolic adaptation, and therapeutic resistance." (PMID 42245660, 2026). "Through the synthesis of a degrader library, we identify and characterize potent USP7 PROTACs for each cancer type." (PMID 42129197, 2026). "Collectively, these results underscore a central role for USP7 in modulating multiple alkylation repair pathways across different cancer types." (PMID 40835840, 2025). "Given the multifaced nature of USP7 in disease, it is becoming an increasingly attractive target for cancer treatment." (PMID 40563391, 2025).
cancer (continued). "Significantly, the PROTAC derivatives were more effective against cancer cells in comparison with the treatment of the sole USP7 inhibitor." (PMID 41157055, 2025). "USP7 has attracted considerable interest as an anticancer target as demonstrated by its major role in tumorigenesis, cancer metastasis, and promoting cancer cell proliferation by stabilizing the Ki-67 protein." (PMID 40247205, 2025). "Depletion of USP7 has previously been shown to inhibit tumor progression in various cancers in murine models, and MGMT knockdown in GBM cell-based models reinforces the role of MGMT in TMZ resistance." (PMID 40835840, 2025). "USP7 is critically involved in cancer development, mediating the deubiquitylation (and therefore the stabilization) of oncogenic proteins such as MDM2 and c-Myc, and influencing growth factor TGF-β, which promotes cell survival and proliferation." (PMID 41157055, 2025). "USP7 overexpression has been reported in numerous malignant tumors as a predictive marker of tumor progression and poor prognosis." (PMID 41157055, 2025). "This dual activity reflects its complex role in cancer biology, where USP7 can either promote or suppress tumor development depending on the cellular context." (PMID 41157055, 2025). "USP7 is increasingly gaining attention due to its potential as an important target in cancer therapy." (PMID 40006058, 2025). "Ubiquitin-specific protease 7 (USP7) is a key regulatorof tumorsuppressors, oncoproteins, and epigenetic machinery, making it a compellingtarget for cancer therapy." (PMID 41210757, 2025). "The experimental validation of USP7 as a potential therapeutic target for cancer reversion, identified through REVERT, provides compelling evidence for the efficacy of dynamic network modeling of tumor transition states." (PMID 39840939, 2025). "In recent years, USP7 inhibitors have attracted considerable attention in cancer therapy owing to the essential function of USP7." (PMID 40006058, 2025). "Overall, these studies highlight the importance of USP7 inhibitors in combination therapies as potential novel therapeutic agents effective against various types of cancer." (PMID 41157055, 2025). "In this context, USP7 plays a dual role, acting as both a tumor promoter and a tumor suppressor depending on the cancer type." (PMID 41157055, 2025). "By bridging structure-based design with pharmacologicalrelevance, our study provides a robust foundation for future in vitro investigations and paves the way for the expediteddevelopment of USP7-targeted therapies for cancer treatment." (PMID 41210757, 2025). "By combining the scores for cancer dependency and normal signature enrichment, we identified USP7 as the optimal target gene for cancer reversion." (PMID 39840939, 2025). "For instance, in neuroblastoma, USP7 facilitates the growth and survival of cancer cells by deubiquitinating and stabilizing N-myc." (PMID 40389405, 2025). "There are studies indicated that USP7 emerges as a potential therapeutic target for cancers, as it plays an important role in the development of tumorigenesis by stabilizing multiple cancer-relevant proteins." (PMID 40568598, 2025). "USP7 is overexpressed in a variety of human cancers, thus it has gradually become a new target in cancer therapy and small molecule inhibitors for USP7 are being developed." (PMID 37867415, 2024). "Mechanistically, MOTS‐c exerted anti‐cancer effects by attenuating USP7‐mediated deubiquitination of LARS1 and promoting LARS1 degradation." (PMID 39321430, 2024).
cancer (continued). "The effects of USP7 on the proliferation of cancer cells were determined by MTS and colony formation assays." (PMID 39346740, 2024). "Although the preclinical efficacy of small-molecule USP7 inhibitors was demonstrated in vivo and the synergistic effect of combining USP7 inhibition with cancer immunotherapy appears promising, the field seems to be at its infancy." (PMID 39430244, 2024). "First, increased USP7 expression is positively correlated with the severity and poor prognosis of multiple cancers, suggesting a pivotal role for USP7 in cancer progression." (PMID 39767641, 2024). "Accumulating evidence indicates that the expression of USP7 is abnormally high in various cancer cells." (PMID 39346740, 2024). "Surprisingly, MDM2 antagonists did not modulate VEGF expression in fibroblasts, suggesting a difference in the USP7 mode of action between cancer cells and fibroblasts." (PMID 38602256, 2024). "Numerous preclinical studies have demonstrated the anticancer effects of USP7 inhibitors (USP7i) in multiple types of cancer using in vitro and in vivo models." (PMID 38474017, 2024). "The ubiquitin-specific protease 7 (USP7, also known as HAUSP) is widely recognized as a critical molecule participating in cancer development, growth, chemoresistance, and metastasis." (PMID 38474017, 2024). "Silencing USP7 leads to decreased PD-L1 expression and increased T-cell-mediated cancer cell destruction." (PMID 38474186, 2024). "Ubiquitin-specific protease 7 (USP7) belongs to the deubiquitinase family and participates in the malignant processes of various cancers by targeting key cancer proteins." (PMID 39062505, 2024). "At least five DUBs were reported to stabilize PD-L1 in different cancers, including USP7, USP9X, USP22, CSN5 and OTUB123,37–40." (PMID 38167274, 2024). "The full anti‐tumour effects of USP7 inhibition can therefore only be assessed in an immune‐competent setting in vivo, such as in a syngeneic cancer model." (PMID 38602256, 2024). "USP7, a most widely studied deubiquitination enzyme yet, is identified to perform oncogenic activity to facilitate cancer growth and is detrimental to the immune response to cancer." (PMID 38625581, 2024). "The expression patterns and functional differences of USP7 in different cancer types are mainly reflected in its mechanism of action and signaling pathways in tumor progression." (PMID 39767641, 2024). "As a druggable target for cancer therapy, many molecules have been found to target USP7 in recent years." (PMID 39346740, 2024). "Mechanistically, MOTS‐c exerts anti‐cancer effects by attenuating USP7‐mediated deubiquitination of LARS1 and promoting LARS1 degradation." (PMID 39321430, 2024). "For instance, USP7 is one of the representative DUBs that have been widely studied in cancer research." (PMID 39329115, 2024). "By modulating the interactions and stability of key players in epigenetic regulation, USP7 plays a crucial role in preserving cellular health and preventing disease progression, particularly in cancer." (PMID 39051184, 2024).
cancer (continued). "USP7 is closely related to the occurrence and development of many cancers and is a promising anticancer target." (PMID 38276639, 2023). "USP7 has been shown to play an important role in the development, progression, and therapeutic response of multiple cancer types." (PMID 37762082, 2023). "Pharmacological inhibition of USP7 has been achieved during the last decade, and multiple novel agents (HBX42108, HBX19818, HBX28258, P5091, and P22077) have been reported to inhibit USP7 in cancer cells." (PMID 37762082, 2023). "In several types of cancer, such as gastric tumors, overexpression of USP7 has been observed, and its expression levels exhibit a positive relevance to PD-L1 expression." (PMID 37658402, 2023). "Studies in mice have demonstrated that pharmacological inhibition of USP7 suppressed the growth and metastasis, promoted cancer cell death in vitro and in vivo." (PMID 37946202, 2023). "USP7 is highly expressed in a variety of tumors and is thought to play a major role in cancer development." (PMID 38276639, 2023). "To further test this, we generated in vivo xenograft tumors of the parental and USP22-Ko A549 cancer cells in mouse, and then the xenografts were treated with a USP7-specific inhibitor P5091 at the previously reported concentration." (PMID 37946202, 2023). "Pharmacological inhibition of USP7 in cancer cells has been shown to strongly increase the accumulation of polyubiquitinated proteins." (PMID 37874827, 2023). "The cytarabine plus USP7 inhibitor P22077 combination can work synergistically to promote anti-leukemic action, which assist cancer cells overcome chemoresistance." (PMID 37658402, 2023). "Silencing USP7 decreases PD-L1 expression on cell surfaces, and augments the T cell-mediated killing of cancer cells." (PMID 37415977, 2023). "In the study, we found that targeting USP7 via either siRNA-mediated knockdown or pharmaceutical inhibitors dramatically upregulates USP22 in cancer cells." (PMID 37946202, 2023). "USP7 is a promising target for cancer therapy as its inhibition is expected to decrease the function of oncogenes, tumor suppressor function, and enhance immune function." (PMID 37740002, 2023). "Scientists have made significant advances in understanding how USP7 modulates cancer patients’ immune response in recent years." (PMID 37658402, 2023). "Prior studies have reported that USP7 stabilizes EZH2 via deubiquitination in different types of adult cancers." (PMID 37762082, 2023). "Almac4 is a highly potent and selective small-molecule inhibitor of USP7 that has shown significant antitumor activity in preclinical models of cancer." (PMID 37762082, 2023). "A significant positive correlation between USP7 and SAMHD1 expression was identified in all three tumor types, suggesting that the existence of the USP7-SAMHD1 axis in various human cancers." (PMID 37081042, 2023). "Another study suggested that oxidative and endoplasmic reticulum (ER) stress contributes to USP7 inhibitor-mediated apoptosis in cancer cells." (PMID 37946202, 2023).
cancer (continued). "We expect this work to be a step forward to making USP7 inhibition an alternative and effective therapeutic pathway in cancer." (PMID 37847342, 2023). "USP7 inhibitor treatment suppresses growth of patient-derived cancer organoids carrying APC truncations in vitro and in xenografts." (PMID 36669491, 2023). "In summary, in this study, we have identified a “feedback” of upregulation of USP22 upon USP7 inhibition in cancer cells." (PMID 37946202, 2023). "To explore the alteration of USPs in osteoclastogenesis, we focused on the alteration of Ub-specific proteasome 7 (USP7), a potential target for cancer treatment." (PMID 37199589, 2023). "Abrogation of USP7 impaired the interaction between PD-1 and PD-L1, leading to sensitization of cancer cells to T cell killing in cancer cells and in mice." (PMID 37215134, 2023). "The effectiveness of USP7 inhibitors hasn't been proven in a carefully chosen cancer patient population employing immunological and genetic biomarkers which can represent the complicated biological functions of USP7." (PMID 37658402, 2023). "Ubiquitin-specific-processing protease 7 (USP7) is a promising target protein for cancer therapy, and great attention has been given to the identification of USP7 inhibitors." (PMID 36631899, 2023). "USPs deubiquitinases such as USP1, USP2, USP7, USP9x and USP14 have been implicated in cancer onset and progression." (PMID 36771100, 2023). "SiRNA-mediated knockdown of USP7 significantly suppressed the parental A549 and H1299 cancer cells, and further suppressed the USP22-Ko A549 and H1299 cells." (PMID 37946202, 2023). "We further demonstrated that blockade of USP7 by its specific inhibitor P5091 sensitizes cancer cells to cisplatin using a nude mice model, thus further indicating its potential role in chemotherapy sensitivity." (PMID 37081042, 2023). "Overexpression of ubiquitin specific protease 7 and 22 (USP7 and USP22) are associated with malignancy, therapy resistance, and poor prognosis in many cancers." (PMID 37946202, 2023). "USP7, a member of ubiquitin-specific processing proteases, was regarded as a biomarker for predicting metastasis and recurrence of several malignant tumors." (PMID 36878903, 2023). "On the basis of these researches, more and more studies on applications of USP7 inhibitors in cancer immunity has emerged." (PMID 37658402, 2023). "Preclinical study shows promising results of USP7 inhibitor in treatment of experimental cancer models." (PMID 37946202, 2023). "Further, SAMHD1 is upregulated in various early-stage human carcinomas and positively correlated with USP7." (PMID 37081042, 2023).